MUC2 (mucin 2, oligomeric mucus/gel-forming)
Diseases named in the same sentence as MUC2 in open-access papers (continued):
Sharing a sentence is not in itself a finding about the gene and the disease.
colon carcinoma (continued). "In addition, as a result of introducing MUC2-siRNA into a colon cancer cell line with high expression of the MUC2 gene, the cell death rate from heat and anticancer agents increased 40% in comparison with colon cancer cells in which scrambled siRNA had not been introduced." (PMID 22266876, 2012). "The MAbs reacted with synthetic MUC2 VNTR peptides but not synthetic MUC1 or MUC3 VNTR peptides, and showed specific reactivity in Western blotting with a high molecular weight protein produced by the LS174T colon carcinoma cell line." (PMID 8512804, 1993).
colorectal cancer (87 papers, 2004 to 2026). A primary or metastatic malignant neoplasm that affects the colon or rectum. "A previous study showed that the expression of MUC2 and TFF3 is decreased in patients with colorectal cancer; therefore, MUC2 and TFF3 are used as diagnostic markers for colorectal cancer." (PMID 40002076, 2025). "The expression and O-glycosylation alterations of MUC2 mucins have been implicated in colorectal cancer." (PMID 38979515, 2024). "Alterations in MUC2 expression have been implicated in various gastrointestinal disorders and malignancies, including colorectal cancer (CRC)." (PMID 39926604, 2024). "For instance, MUC2 overexpression correlates with resistance to concurrent chemoradiotherapy in colorectal cancer and has been linked to poor prognosis." (PMID 37626856, 2023). "High expression of Mucin 2 (MUC2) has been associated with longer disease-free survival in colorectal cancer patients." (PMID 31337362, 2019). "In conclusion, the current study suggests that a low level of MUC2 expression is an independent factor of poor prognosis in colorectal cancer and also associated with later TNM stage, presence of lymph node metastasis, rectal tumor site, and large tumor size." (PMID 29967641, 2018). "The important protective role of Mucin 2 (Muc-2) in colorectal cancer has been demonstrated in Muc2-deficient mice, which develop spontaneous intestinal and rectal tumors that eventually progress to carcinomas." (PMID 28410235, 2017). "The loss of MUC2 expression has been related to recurrence of colorectal carcinoma while the positive expression of MUC2 has been associated with longer survival." (PMID 27148394, 2016). "The studies from us have shown that genetic deletion of the Muc2 gene is sufficient to cause chronic colitis and rectal inflammation at early stage, and leads to colorectal cancer formation at late stage." (PMID 25166914, 2014). "Our previous studies have demonstrated that genetic deletion of the Muc2 gene causes colorectal cancers in mice." (PMID 24941171, 2014). "And the chronic inflammation facilitated Apc-mutation-caused gastrointestinal tumor formation in the Apc/Muc2 double gene knockout mouse model of colorectal cancer." (PMID 25166914, 2014). "MUC-2 is down-regulated in many colorectal cancers and is associated with the differentiated state of colonic epithelia." (PMID 23829413, 2013). "Muc2 is thus involved in the suppression of colorectal cancer but the question “cause or consequence” of Muc2 role in tumor suppression remains to be answered." (PMID 24281201, 2010). "It has been speculated that altered MUC2 expression, in combination with genetic factors, may increase colorectal cancer (CRC) risk by creating a microenvironment suitable for tumor growth and metastasis." (PMID 40699805, 2025). "Taken together, this study reveals that diet- and sex-specific changes in MUC2 expression may be associated with an increased risk of colorectal cancer." (PMID 38347027, 2024). "Similarly, there is evidence suggesting that the expression of MUC2 is associated with invasion and metastasis in various malignant tumors, including gastric cancer, prostate cancer, and colorectal cancer." (PMID 36674608, 2023). "It was found that Muc2 knockout in mice could cause inflammation that eventually leads to colorectal cancer." (PMID 36468853, 2022). "This is interesting, because the loss of Muc-2 expression contributes to the colorectal cancer progression, and this loss could be facilitated by Wnt/β-catenin signaling." (PMID 28410235, 2017). "Since genetic deficiency of the Muc2 gene in mice causes colorectal cancer formation, the decreased expression of miR-27a in colonic epithelial cells could be involved in the carcinogenesis." (PMID 25166914, 2014). "For instance, miR-302c-3p targets TIM4 in cervical cancer, miR-144 targets MUC2 in colorectal cancer, miR-706 and miR-665 target ASGR2 and CD44 in gastric cancer, and miR-532-3p and miR-593-5p target MAPK genes in lung cancer." (PMID 41378310, 2025).
colorectal cancer (continued). "MUC2 is expressed by healthy goblet cells in the intestine but is overexpressed in gastric and colorectal cancers, 45]." (PMID 40599846, 2025). "The research conducted in this study aimed to unravel the intricate role of MUC2, a mucin protein, in the context of colorectal cancer (CRC), with a specific focus on its influence on immune response dynamics and cellular behavior." (PMID 39926604, 2024). "While MUC2 has been suggested to be specific for the GI tract and mainly expressed in colorectal cancer, especially mucinous colorectal AC, MUC6 has been reported to be positive more often in upper GI tract and pancreatic AC." (PMID 37349623, 2024). "Our study is the first to demonstrate that MUC2 functions as a physical barrier to immune infiltration in colorectal cancer (CRC) in vitro." (PMID 39926604, 2024). "MUC2 positivity was found in 51% of colorectal cancers and 0% of mucinous ovarian cancers, respectively." (PMID 37664708, 2023). "The biological relevance of Muc2 was demonstrated in Muc2-knockout mice which develop adenocarcinomas and colorectal cancer." (PMID 36875083, 2023). "MUC2 expression has been described to also vary from colorectal carcinomas of different histological types." (PMID 37830585, 2023). "More specifically, Amuc_1434 leads to the degradation of Muc2, a gene that leads to the production of mucin 2, an intestinal protein previously shown to be significantly increased in colorectal cancer." (PMID 34842660, 2021). "In our cohort of stage II colorectal cancer patients, we identified a role for MUC2 as predictor of response to adjuvant chemotherapy." (PMID 33823840, 2021). "In the current study, we investigated the effect of Amuc_1434* on the growth of Muc2-expressing colorectal cancer LS174T cells." (PMID 32403433, 2020). "Since Muc2 is related to the progress of CRC, we investigated the effect of Amuc_1434* on the proliferation, cycle, and apoptosis of LS174T colorectal cancer cells expressing Muc2 and the possible mechanism of action in the current study." (PMID 32403433, 2020). "(2007), MUC2 down‐regulation is a marker of tumor progression through the adenoma–carcinoma sequence and survival of colorectal carcinoma." (PMID 30847127, 2019). "The levels of Mucin2 (Muc2) is highly controversial in cancers especially colon and colorectal cancers." (PMID 30326660, 2018). "In vitro studies were conducted using LS174T cells (MUC2-secreting human colorectal cancer cells), PMP explant tissue, and epithelial organoid cultures (colonoids) derived from mucinous appendix cancers." (PMID 29290997, 2017). "The MUC profile in the FCCTX subset was more akin to that of unselected colorectal cancers with MUC2 expression reported in 40–54%, MUC5AC in 6–10% and MUC6 in 4%." (PMID 28824332, 2017). "MUC2 has a known tumor suppressor role as seen in colorectal cancer where MUC2 suppresses inflammation." (PMID 28978023, 2017). "As reported by us, cytokines were significantly increased and miR-138, 145, 146a, and miR-150 were significantly decreased in Muc2-/- mouse colon and human colitis and colorectal cancer." (PMID 28441730, 2017). "Using a colorectal cancer mouse model Muc2 knockout mice and miRNA array analysis on colonic epithelial cells, we have found that miRNAs were differentially expressed in mouse colonic epithelial cells, including 20 downregulated and 71 upregulated miRNAs." (PMID 28441730, 2017). "The suppression of MUC2 has also been found to enhance the proliferation and invasion of colorectal cancer cells." (PMID 27148394, 2016).
colorectal cancer (continued). "The synthesis of MUC2, the main intestinal secreted mucins, has been shown to be suppressed in colorectal cancer and its metastases." (PMID 26500890, 2015). "Using a miRNA array profile we have found that miRNA were differential expressed in colonic epithelial cells of a colorectal cancer mouse model, the Muc2 gene knockout mice." (PMID 25166914, 2014). "In contrast, the suppressive effect of MUC2 in colorectal cancer (CRC) was demonstrated in MUC2-null mice, suggesting that it has a protective effect in the colon." (PMID 25322805, 2014). "For instance, several randomized controlled trials have demonstrated significant cancer prevention of selenium in colorectal cancer and in Muc2/p21 mouse model of intestinal cancer reported recently by us." (PMID 23327547, 2013). "Among colorectal carcinomas, MUC2-positive tumours have been reported to have a relatively good prognosis, with a low incidence of liver metastasis." (PMID 15354218, 2004). "Furthermore, the present study demonstrates that two genes in colorectal cancer (CRC) cells are affected by MPs: MUC2 and TIM4." (PMID 41378310, 2025). "Besides, MUC2 was downregulated in general colorectal cancer and highly expressed in mucinous adenocarcinoma." (PMID 33776762, 2021). "However, the expression of MUC2 in colorectal cancer is different based on the histopathological type." (PMID 32695780, 2020). "Of note, Muc2 glycoprotein plays an essential role in epithelial protection since Muc2 knockout mice spontaneously develop severe colon inflammation and inflammation-induced colorectal cancer." (PMID 33171587, 2020). "Thus, the main objective of this study was to explore the effects of Amuc_1434* on LS174T in colorectal cancer cells expressing Muc2." (PMID 32403433, 2020). "Similarly, a recent study showed increased MUC2 expression in response to hypoxia in LS174T colorectal cancer cells." (PMID 30755679, 2019). "The reliability of MUC2 as a prognostic marker in colorectal cancer (CRC) is controversial." (PMID 29967641, 2018). "Aberrant O‐glycosylation may alter oncogenic behaviours in colorectal carcinomas by impairing the expression or stability of intestinal mucins, primarily MUC2." (PMID 29999571, 2018). "Colorectal cancers are the only tissues to display a significant decrease in MUC2." (PMID 28978023, 2017). "For instance, the study of Muc2 knock-out mice, which lack Muc2, the most abundant secreted gastrointestinal mucin, led to the discovery of the link between this protein and suppression of colorectal cancer." (PMID 25561744, 2015). "Here, we investigated the impact of mulberry fruit (MBF) extracts on lipopolysaccharide (LPS)-induced inflammatory responses in RAW 264.7 macrophages, and the therapeutic efficacy of MBF diet in mice with dextran sulfate sodium (DSS)-induced acute colitis and MUC2−/− mice with colorectal cancer." (PMID 26615818, 2015). "Thus, mithramycin, a Sp1 binding site inhibitor, effectively blocks the MUC2 expression in colorectal cancer." (PMID 24886459, 2014). "We also observed a strong down-regulation of the Muc2 gene, coding for Muc2, the most abundant mucin secreted by normal colonocytes, in agreement with experimental and clinical reports documenting defective mucin production in colorectal cancer." (PMID 20459814, 2010). "Interestingly, most MUC2+ colorectal cancer cells were also EPHB2-/ERBB3+." (PMID 26367378, 2015). "RhoB knockdown using siRNA in human colorectal cancer cell line SW480 was carried out to further validate the effects of RhoB in vitro, and increased Muc2 and Ki67 protein levels in SW480 cells with RhoB knockdown were observed." (PMID 36114582, 2022). "Both of PEAC and MCAC can be present with a morphology of colorectal carcinoma, and CK20, CDX2 and MUC2 can be immunohistochemically positive in both of them." (PMID 32429938, 2020). "However, the interaction between MUC2 and IL-6 in colorectal cancer metastasis remains unclear." (PMID 28725043, 2017).
colorectal cancer (continued). "The current data collectively supports the notion that higher expression of MUC2 and MUC5AC confers genetic and molecular features on colorectal carcinomas that incur adverse consequences in relation to treatment response and clinical outcome." (PMID 26436698, 2015). "In appendiceal carcinoma, MUC3, MUC6 and MUC16 had lower expression, MUC2 expression was markedly higher, and MUC1 expression was higher than the respective rates in colorectal carcinoma." (PMID 25551773, 2014). "In colorectal carcinoma, these rates are MUC1, 24–32%; MUC2, 38%; MUC3, 74%; MUC4, 94%; MUC5AC, 34–50%; MUC6, 39%; and MUC16, 64%." (PMID 25551773, 2014). "Immunohistochemical staining showed that the tumoroids from all the groups were positive for β‐Catenin, CDX‐2, CK20, and E‐Cadherin, and negative for MUC‐2, which were the featured markers of colorectal cancers, as shown in the Protein Atlas database." (PMID 40611658, 2025). "MUC2 was negative in all primary lung cancers, but only positive in a limited number of pulmonary metastases including 10 colorectal cancers (whereof 8 were mucinous), 3 appendix AC, 1 cholangiocarcinoma, and 1 ductal breast cancer." (PMID 37349623, 2024). "Muc2 is involved in the development of colorectal cancer (CRC), which is a major health problem in the world, with more than 1.2 million patients diagnosed with colorectal cancer each year and nearly 600,000 deaths." (PMID 32403433, 2020). "In mucinous and nonmucinous colorectal cancer tissues, MUC2 expression is downregulated by methylation of CpG islands in the specific regions of MUC2 promoter." (PMID 31930146, 2019). "We investigated the core protein-expression levels of MUC2, MUC5AC, MUC6, and CD10 because altered expressions of these proteins may be significantly correlated with the biological behavior of colorectal carcinoma and, possibly its prognosis." (PMID 30458818, 2018). "Nishikawa and colleagues previously demonstrated cAMP-mediated elevation of MUC2 and MUC5AC expression in stably transfected HT29 colorectal cancer cell line expressing GNAS, thereby supporting the role for GNAS expression and cAMP/PKA signaling pathway in the regulation of mucin production." (PMID 29290997, 2017). "Both ITACs and colorectal carcinomas express CK20, CDX-2, villin and MUC2, but the expression of CK7 in a tumor may be suggestive of ITAC." (PMID 28321774, 2017). "In addition to MUC2, the abnormal expression of MUC5AC is also observed in colorectal cancer." (PMID 40699805, 2025). "Interestingly, the introduction of the mutant GNAS into a colorectal cancer cell line markedly induced MUC2 and MUC5AC expression, but did not promote cell growth either in vitro or in vivo." (PMID 24312577, 2013).
gastric cancer (47 papers, 2004 to 2025). A primary or metastatic malignant neoplasm involving the stomach. "The association between co-function of PGC, MUC1 and MUC2 and the occurrence and development of gastric cancer and precancerous disease needs to be clarified in the future." (PMID 23937908, 2013). "Here, we report that allelic variations in the minisatellites of MUC2 are related to susceptibility to gastric cancer." (PMID 18000536, 2007). "The association of SOX9 expression with MUC2 (an intestinal differentiation marker) expression is consistent with its role in Helicobacter pylori infection and overrepresentation of intestinal-type histology in Helicobacter pylori-related gastric cancers." (PMID 35221802, 2022). "Finally, MUC2 expression was shown to be associated with tumor differentiation and invasion in gastric cancers." (PMID 33400739, 2020). "In conclusion, KLF4 is essential for normal homeostasis of antral stem cells; loss of KLF4 and expression of MUC2 could be important markers for gastric cancer diagnosis." (PMID 27277677, 2016). "This is the first report in which minisatellites have been characterized in detail for the complete MUC2 gene and our observations suggest that the loci of MUC2 minisatellites may function as indicators of cancer risk in gastric cancers." (PMID 18000536, 2007). "In gastric cancer (GC), intestinal metaplasia (IM) is a common precursor lesion, but its relationship to the MUC2/MUC5AC/CDX2 axis is not completely understood." (PMID 37240039, 2023). "We found that, in addition to genes involved in mucin processing and secretion, MUC2 up-regulation is a multi-cancer biomarker of mucinous histology and is regulated by DNA methylation in colorectal, breast and stomach cancer." (PMID 33947930, 2021). "For instance, miR-9 is responsible for gastric malignancies by targeting CDX2, conferring among others to enhanced proliferation of gastric cancer cells and MUC2 expression." (PMID 34183045, 2021). "Previous research evaluating genetic variability in mucin genes of patients presenting gastric cancer precursor lesions has also shown that the genetic variability of MUC2 influences the progression of the lesions in H. pylori infected patients." (PMID 33322136, 2020). "Numerous studies have shown that the expression of MUC2 is related to the invasion and metastasis of various malignant tumors, including gastric cancer, gallbladder cancer, breast cancer, ovarian cancer, and lung cancer." (PMID 31950990, 2020). "And MUC2 and Villin are also important gastric epithelial cell markers for phenotypical and histological detection of gastric cancer." (PMID 28764790, 2017). "Helicobacter pylori infection related long non-coding RNA (lncRNA) AF147447 inhibits cell proliferation and invasion by targeting MUC2 and up-regulating miR-34c in gastric cancer." (PMID 29221147, 2017). "In this case, the similar cellular morphology and immunoreactivity of CK7, CK20, Villin, and MUC2 demonstrated the gingival metastasis originated from his gastric carcinoma." (PMID 28764790, 2017). "To understand the clinical relevance of these findings, we analyzed the expression of KLF4 and MUC2 in human gastric cancer." (PMID 27277677, 2016). "In a subset of human gastric cancer, the expression of KLF4 is negatively associated with MUC2 expression." (PMID 27277677, 2016). "The expression of KLF4 and MUC2 was further analyzed in human gastric cancer tissues and adjacent normal tissues." (PMID 27277677, 2016). "Staining was used to detect Cdx1, Cdx2, Muc2 and Muc5AC and it was revealed that Cdx1 and Cdx2 were consistently expressed in IM and in a subset of gastric carcinomas." (PMID 19412438, 2007). "Mucin genes expressed in normal gastric mucosa include MUC1, MUC5AC and MUC6, whereas MUC2 is expressed aberrantly in 30% of gastric carcinomas." (PMID 18000536, 2007).